CD40 (CD40 molecule)
Diseases named in the same sentence as CD40 in open-access papers (continued):
Sharing a sentence is not in itself a finding about the gene and the disease.
tumor (continued). "However, when adding a CD40 agonist to ICIs and radiotherapy, not only a reduction in the irradiated tumor but also a decrease in the unirradiated tumor size was observed." (PMID 37895882, 2023). "However, the potential of tumor and CD40 agonist to promote the immunosuppressive activity of B cells was markedly suppressed GSK." (PMID 37291146, 2023). "To explore the potential therapeutic implications of this finding, we assessed whether active NRF2 within leukocytes of the tumor microenvironment is sufficient to induce resistance to anti-CD40 therapy." (PMID 38060331, 2023). "Complete regression of the irradiated tumor was observed in 42% of the mice treated with RT+CTLA4i+anti-CD40; highly significant delayed progression of the abscopal tumor was also observed in this group, with two partial responses and one complete response reflecting in increased survival." (PMID 37620372, 2023). "Thus, we first asked if tumor control was mediated by CD8 T cells in mice treated with RT+CTLA4i+anti-CD40." (PMID 37620372, 2023). "Activation of CCL22+ cDC1 cells following anti-CD40 treatment may elevate the occurrence of IFN-γ-producing tumor-infiltrating CD4+ Th cells." (PMID 38012715, 2023). "Results indicated that a significant reduction in distant tumor volume (96–98%) occurred with increased survival with increased recruitment of effector T cells leading the authors to conclude anti‐CD40 antibody to be an effective immunoadjuvant with radiation to potentiate abscopal responses." (PMID 36411943, 2023). "CD40 expression can have different consequences depending on tumor type." (PMID 37970926, 2023). "CD40 agonists have been shown to trigger anti-tumour immune effects and combination treatment with olaparib and/or anti-PD-L1 antibodies may be a novel strategy in cancers with HRR defects." (PMID 37365284, 2023). "Furthermore, MC38‐tumor‐infiltrating cDC1 also showed upregulated CD40, CD80, CD86, and MHC‐II expression after RA and anti‐PD‐1 combination treatment." (PMID 36876644, 2023). "Likewise, the expression of CD40L on tumor-cell-derived EVs promotes the binding to CD40 expressed on DCs, inducing their uptake and enhancing the tumor antigen presentation of T cells." (PMID 37175226, 2023). "This outcome could be explained by low expression of mesothelin on tumor cells, that would limit bsAb accessibility to the tumor and thus its ability to crosslink the CD40 receptor, which is required for CD40 signaling." (PMID 35911742, 2022). "GBM cells secreted CD40L around the tumour and reprogrammed MSLCs through CD40." (PMID 35908277, 2022). "While the ability of CD40 stimulation to support T cell responses is generally considered to be dependent upon its action on DCs, it is important to recognize that CD40 stimulation can target other cells within the tumor microenvironment and the tumor-draining lymph nodes." (PMID 34282297, 2022). "Indeed, in the bilateral PDAC model, anti-CD40-ISV as well as K3-SPG-ISV suppressed tumor growth on both the treated and untreated sides, demonstrating the abscopal effect of each respective monotherapy." (PMID 35136110, 2022). "Preprocessed MHC class I- or MHC class II-restricted peptides will be less dependent upon engulfment by DCs or macrophages, while recombinant proteins or tumor lysates will likely be best deployed in the context of relatively immature DCs that are subsequently activated via CD40 stimulation." (PMID 34282297, 2022). "Because, high expression of CD40L, CD40 and LOX may reflect tumour malignancy in GBMLGG dataset, thus CD40L, CD40 and LOX expressions are associated with patient clinical outcomes." (PMID 35908277, 2022). "In addition, other ICRGs, including agonists of stimulatory checkpoint pathways, inducible ICOS, CD40, or molecules targeting tumor microenvironment (TME) components, are coming into our attention." (PMID 36253800, 2022). "The CD40/CD40L axis is also important in an immunosuppressive tumor microenvironment." (PMID 35806328, 2022).
tumor (continued). "We have shown that three i.t. injections of IL-2 modified tumor blood vessels and recruited CD8+ T cells into the tumor bed whilst three i.t. injections of IL-2 combined with an agonist anti-CD40 antibody recruited a massive and simultaneous infiltrate of neutrophils and T cells." (PMID 36466911, 2022). "Intriguingly, CD40 stimulation reduced PD1 expression on T cells but also decreased their expression of TCF-1, which has been associated with pluripotent T cells within the tumor microenvironment." (PMID 34282297, 2022). "For this purpose, we generated CD40- and 41BB-specific antibody variants with an anchoring domain (AD) which binds to the cell surface-exposed checkpoint molecule PDL1 which is preferentially expressed in the tumor." (PMID 35198053, 2022). "Agonist monoclonal anti-CD40 antibodies can act on DCs and immature myeloid cells to increase their antigen-presenting capacity, maturation and activation potential (called licensing), thereby shifting the balance from tolerance to anti-tumor immunity." (PMID 35788566, 2022). "In this study, neutrophil based interventions were able to suppress CD40 agonist associated liver damage without negatively impacting on the tumour response." (PMID 35454819, 2022). "They found that CD40 agonist/IL15 is the most effective for suppressing tumor growth." (PMID 35453676, 2022). "Additionally, the expression of tumor-associated antigens such as MHC class I and class II molecules, as well as costimulatory CD80 and CD40, is also augmented by HDAC inhibition, so these tumors get more susceptible for immunotherapy." (PMID 35055045, 2022). "However, in time-independent study, the expression levels of CD40 on Lin− population were significantly increased, compared to untreated tumour-bearing mice." (PMID 36551739, 2022). "Interestingly, by artificially expressing the CD40L as constitutive co-stimulatory molecule on the surface of CAR-T cells, the priming and clonal expansion of endogenous tumor-reactive T cells can be facilitated via the stimulation of CD40-expressing APCs." (PMID 35053463, 2022). "For example, the finding that the location of immune activation is associated with distinct outcomes, i.e., antitumor activity vs. systemic toxicity, advanced approaches aiming to direct CD40 agonism selectively to the tumor microenvironment (TME) to avoid toxicity." (PMID 35911742, 2022). "Moreover, CD40 activated macrophages were shown to infiltrate tumors and destroy tumor stroma via tumoricidal activity." (PMID 35715855, 2022). "Overall, tumor response rates with single-agent CD40 monoclonal antibodies have been low to date." (PMID 36031601, 2022). "In addition, combination with properly sequenced chemotherapy results in release of tumor antigens that augment the CD40 agonistic effect." (PMID 36077755, 2022). "In this study, we aimed on to exploit the high agonism of AT-bound αCD40- and α41BB-AD fusion proteins to generate CD40 and 41BB agonists that not only intimately link checkpoint inhibition with CD40/41BB engagement but also act preferentially in the tumor to reduce so potential off-tumor effects." (PMID 35198053, 2022). "However, compared to untreated tumour-bearing mice, an increase in the expression levels of CD40 was observed on this Lin− population after ECT treatment." (PMID 36551739, 2022). "Similarly, the mechanism of anticancer potential is plausibly mediated through upregulation of STAT1 gene (tumor suppressor), and downregulation of IL-6, TNF-α, and CD40 (tumor causing genes) besides other intricate mechanisms." (PMID 36612248, 2022). "Thus, researchers are investigating combination therapies to both promote the anti-tumor effects and inhibit pro-tumor effects of CD40 signaling (Section 4)." (PMID 35456932, 2022). "We further hypothesized that DMXAA could render the tumor microenvironment more permissive and responsive to biological molecules such as agonist anti-CD40 antibody or IL-2 to further enhance the immune response." (PMID 36466911, 2022).
tumor (continued). "Similar tumor microenvironment remodeling as a function of CD40 stimulation has been reported by other groups in different models, indicating a common theme that above and beyond DC priming, CD40 can promote a proimmunity landscape within tumors." (PMID 34282297, 2022). "Indeed, proapoptotic CD40 effects have been described in various tumor entities but antiapoptotic CD40 activities have been reported as well." (PMID 36361658, 2022). "Likewise, CD40 agonist, combined with CSF-1R, blockades reconditions TAMs and promotes potent anti-tumor immunity." (PMID 36303138, 2022). "However, the CCL2-induced elevation of GC tumor volume and weight was greatly decreased with anti-CD40 mAb or CD40 ×HER2 bsAb treatment." (PMID 35851310, 2022). "However, it is currently unclear which cell population contributes to increased CD40 expression within the tumor." (PMID 35806358, 2022). "Together, the results support a deeper interrogation of tumor-specific T cell differentiation following CD40 agonist in cDC1-sufficient hosts as our results suggest that competition among cDC1s and macrophages for tumor antigen may shape tumor immunity." (PMID 35393950, 2022). "CD40 agonist primes tumor-specific CD8+ T cells via monocytes/macrophages in Batf3–/– mice." (PMID 35393950, 2022). "However, attempts to enhance DMXAA-induced anti-tumor responses by combination with an agonist anti-CD40 antibody or IL-2 reduced efficacy." (PMID 36466911, 2022). "Since PDL1 expression is particular prominent in many tumors, the conditional membrane PDL1-restricted mode of CD40 and 41BB agonism furthermore promises particular efficient CD40/41BB activity in the tumor and thus reduced dose-limiting off-tumor immune stimulation." (PMID 35198053, 2022). "Moreover, the combination of CSF-1R inhibition with CD40 agonism was able to induce potent T cell-mediated tumor killing in a melanoma model." (PMID 35205732, 2022). "Ligating CD40 on B cells from higher grade malignancies such as large cell lymphoma of B-cell origin or Epstein-virus-induced B-cell lymphoma arrested their growth and even reduced tumor development in animal tumor models." (PMID 35681441, 2022). "CD40 agonism and resulting tumor cell death was shown to be synergic with chemotherapy in murine models: when combined with gemcitabine and administered to mice with established implanted tumors, most mice were cured and resistant to tumor rechallenge." (PMID 35456932, 2022). "Thus, panobinostat is postulated to induce anti-tumor immunity on the level of bulk tumor, whereas venetoclax/anti-CD40 induces anti-tumor immunity on the level of resistant, tumor-initiating CSCs." (PMID 35788566, 2022). "Additionally, FcγR-independent therapeutics including anti-TNFR and anti-CD40 monoclonal antibodies with human IgG2 agonistic activity have been developed and have showed encouraging clinical outcomes in late stage tumor patients." (PMID 35812448, 2022). "Remarkably, at higher doses the FcγR2B-selective human CD40 antibody showed significant hepatotoxicity hindering tumor therapy by systemic application, but the latter could be overcome by intratumoral injection." (PMID 36361658, 2022). "Prior work in tumor-bearing mice showed that the depletion of macrophages using anti-CSF1R antibodies abrogates hepatotoxicity observed when gemcitabine is administered 2 days after a CD40 agonist." (PMID 34101617, 2021). "However, anti-CD40 can also sensitize tumors to chemotherapy by activating a myeloid-dependent immune response that resolves stromal elements of the tumor microenvironment involved in chemoresistance." (PMID 34101617, 2021). "Additionally, agonistic aptamers against 4-1BB, OX40, CD28, and CD40 were developed by the Gilboa laboratory with similar anti-tumor effects in mice to those of mAbs." (PMID 33868786, 2021).
tumor (continued). "Here we assess the expression of CD40 and associations with other mediators of immunity in a variety of tumor types and review the potential of CD40 agonists for cancer treatment, given the promise of enhancing the interplay between innate and adaptive immunity." (PMID 33804039, 2021). "Another interesting concept is the tumor-targeted activation of CD40." (PMID 34358141, 2021). "Similar effects of a CD40 agonist were more recently observed in mice vaccinated with DC loaded with tumor lysate, and such effects could be potentiated in combination with adjuvants such as poly I:C." (PMID 33948686, 2021). "Tumor growth inhibition via macrophages occurs upon CD40 activation." (PMID 34831416, 2021). "Activation of CD40 reprograms macrophages to destroy tumor stroma." (PMID 34290984, 2021). "Fortifying the tumor microenvironment with CD40-ligand/anti-CD40 agonist may further enhance the antitumorigenic effect of checkpoint inhibitors." (PMID 34765538, 2021). "CD40 agonist antibodies can potently activate anti-tumor immunity via multiple mechanisms." (PMID 33392713, 2021). "Thus, activation of CD40 can prevent tumor growth indirectly by anti-tumor immune cell responses or directly by tumoricidal activity such as apoptosis and ADCC." (PMID 33804039, 2021). "CD40 is expressed on dendritic cells, B cells, macrophages and even tumor cells." (PMID 34683963, 2021). "Although previous in vivo studies have demonstrated that CD40 agonist antibody treatment may result in depletion of CD8+ T cells in tumor-bearing mice, these effects could be circumvented by co-administration with a cancer vaccine." (PMID 33948686, 2021). "Several interventions combining IL-15 agents with checkpoint inhibitors, antibodies stimulating immune cell functions (e.g., anti-CD40, anti-CD16), monoclonal antibodies specific for tumor-associated antigens, and immunotoxins have been tested in preclinical models, with promising results." (PMID 33671252, 2021). "Since MBTA therapy incorporates anti-CD40 (which polarizes B cells towards an anti-tumor role), it is reasonable to suggest that B cells drive an anti-tumor immune response through their antigen presentation capacity and also the production of anti-tumor antibodies." (PMID 34439097, 2021). "Tumor cells can undergo apoptosis or growth inhibition after CD40 ligation." (PMID 34683963, 2021). "Sensitivity to CD40 ligation-induced apoptosis might be a new mechanism to eliminate tumor transformation of urothelial cells." (PMID 34899848, 2021). "CD40 agonist antibodies have demonstrated anti-tumor activity but with dose-limiting toxicity." (PMID 34768776, 2021). "Some studies have assessed CD40 agonist’s potential to improve the immunity of T cell to solid tumors and found that CD40 agonists are able to boost T cell response to dimly immunogenic tumor antigens." (PMID 33494834, 2021). "Combination of IL-6 inhibition with CD40 stimulation reverses Mφ-mediated tumor immunosuppression, sensitizes tumors to checkpoint blockade, and extends animal survival in two syngeneic GBM models, particularly inducing complete regression of GL261 tumors after checkpoint blockade." (PMID 34103524, 2021). "Both results are consistent with the hypothesis that RGS markedly enhanced immune surveillance of the tumor through CD40-upregulation." (PMID 34092233, 2021). "More recently, the dual Ang-2/VEGF inhibition has been combined with CD40 or PD-1 immune therapies and showed strong synergistic effects in terms of tumor growth, overall survival, and immune cell activation in several murine tumor models." (PMID 33783686, 2021). "The CD40+SOX10+ cells in each tumor biopsy ranged from 2 to 616 counts." (PMID 34092233, 2021). "Compelling evidence has shown that systemic Flt3L injections could induce tumor-residing cDC1s24,25,27,28 and synergize with radiotherapy and systemic anti-CD40 Ab27." (PMID 34754037, 2021).
tumor (continued). "This also underscores the need to combine CD40 agonist treatment with multiple different tumor antigen peptides, preferably tumor neoantigens, for a potent immune response to be generated against the tumor." (PMID 33948686, 2021). "Notably, in PDX1214 the SOX10 expression pattern matched well with the CD40 expression pattern based upon IHC staining, even though there was only minimal inhibition of tumor growth." (PMID 34092233, 2021). "CSF-1R inhibition combined with CD40 agonism is synergistic in various murine tumor models." (PMID 33804039, 2021). "Moreover, antigen presenting cells (APCs) from Osm−/− tumours expressed higher levels of co-stimulatory molecules such as CD40 and CD86." (PMID 34921158, 2021). "Co-stimulation of innate and adaptive immunity might result in enhanced anti-tumor activity, and CD40 agonistic antibodies have therefore been the subject of intense preclinical and clinical research." (PMID 33804039, 2021). "Agonist CD40 antibodies have induced anti-tumor effects in several tumor models and the effect has been more pronounced when used in combination with other treatments (immune checkpoint inhibition, chemotherapy, and colony-stimulating factor 1 receptor inhibition)." (PMID 33804039, 2021). "In addition to CSF1/CSF1R blockade, macrophage reprogramming using HDAC inhibitors or agonistic anti-CD40 antibodies increases the expression of PD-L1 on macrophages, which limits the anti-tumor effect of reprogrammed TAMs." (PMID 34248982, 2021). "The effect of CD40 agonist antibodies can be further enhanced with radiotherapy, chemotherapy, or cancer vaccines, which are viable approaches for increasing availability of tumor antigens." (PMID 33948686, 2021). "Our findings suggest that dual-targeting IL-6 and CD40 may offer exciting opportunities for reversing Mφ-mediated tumor immunosuppression and improving T-cell-based immunotherapy against GBM." (PMID 34103524, 2021). "In addition, higher IL2, IFN-γ, and TNF families (e.g. CD40) represents a favorable cellular immunity and anti-tumor ability of C3." (PMID 33637086, 2021). "Many synthetic TLR3 agonists have been produced and their potential is being tested as adjuvants for vaccines or in combination with ICB, costimulatory agonist (anti-CD40), anti-angiogenic drug (bevacizumab), radiation, tumor-targeted therapy (oregovomab) or lenalidomide." (PMID 34572013, 2021). "While CSF1R inhibitors and CD40 agonists potently reduce tumor growth in mice, the combined use of Emactuzumab (anti-CSF1R monoclonal antibody) with Selicrelumab (agonistic CD40 monoclonal antibody) in patients with metastatic PDAC has not translated into objective clinical responses (NCT02760797)." (PMID 34201127, 2021). "With the broad pro-inflammatory effects of CD40 and its ligand on dendritic cells and macrophages, and downstream B and T cell activation, agonists of this pathway may enhance the anti-tumor activity of other systemic therapies." (PMID 33804039, 2021). "Notably, there is strong pre-clinical evidence that tumor regression can follow treatment with agonist CD40-targeting antibody." (PMID 34868044, 2021). "CD40 agonists increase the expression of co-stimulatory and antigen-presenting molecules on macrophages and the secretion of pro-inflammatory mediators, which enhances the T cell–dependent anti-tumor effect." (PMID 34248982, 2021). "Five days after tumor inoculation, cGAMP@dual-anti-Exos were injected into mice and the fluorescent signals of Alexa 488 that came from anti-PD-L1 and Alexa 647 that came from anti-CD40 were measured." (PMID 34541546, 2021). "Thus, immunotherapy aiming to improve APC function, e.g., CD40 agonist antibodies, has the potential to provide clinical benefit in tumors that lack tumor-reactive T cell infiltrate due to insufficient APC activation and T cell priming." (PMID 33948686, 2021).